AEBP2 (AE binding protein 2)
Description:
Acts as an accessory subunit for the core Polycomb repressive complex 2 (PRC2), which mediates histone H3K27 (H3K27me3) trimethylation on chromatin leading to transcriptional repression of the affected target gene. Plays a role in nucleosome localization of the PRC2 complex.
Synonyms: MGC17922
Tractability: Small molecule: a structure with a bound ligand is known; a high-quality ligand is known. PROTAC: ubiquitination databases record sites on it; a small molecule that binds it is known.
Gene: Protein-coding gene on chromosome 12 (19,404,045 to 19,720,801, forward strand). Ensembl gene ENSG00000139154.
Subcellular location: Nucleus
Subcellular location (Human Protein Atlas): Nucleoplasm
Pathways (Reactome):
Chromatin organization: PKMTs methylate histone lysines
Gene expression (Transcription): PRC2 methylates histones and DNA
Gene Ontology:
Molecular function: transcription coregulator activity
Biological process: heterochromatin formation; negative regulation of transcription by RNA polymerase II; regulation of transcription by RNA polymerase II
Cellular component: ESC/E(Z) complex; nucleoplasm; nucleus; chromatin
Genetic constraint (gnomAD): Loss-of-function variants: 4 observed, 19.87 expected, observed/expected ratio (o/e) 0.2, 90% interval 0.098 to 0.46. The synonymous counts are far from expectation, so gnomAD's model fits this gene poorly and the ratio says little. Missense variants: 527 observed, 486.55 expected, observed/expected ratio (o/e) 1.08, 90% interval 1.01 to 1.16. Synonymous variants: 271 observed, 190.75 expected, observed/expected ratio (o/e) 1.42, 90% interval 1.29 to 1.57.
Homologues: Orthologues: macaque AEBP2 (99% identical), dog AEBP2 (99% identical), pig AEBP2 (99% identical), chimpanzee AEBP2 (99% identical), mouse Aebp2 (93% identical), rat Aebp2 (93% identical), guinea pig AEBP2 (82% identical), rabbit AEBP2 (57% identical), zebrafish aebp2 (55% identical), tropical clawed frog aebp2 (54% identical). Paralogues in human: GLI2 (22% identical), GLI3 (22% identical), GLIS3 (19% identical), GLI1 (18% identical), GLIS1 (18% identical), ZIC2 (16% identical), GLIS2 (15% identical), ZIC3 (15% identical), ZIC1 (15% identical), ZXDA (14% identical), ZXDB (14% identical), ZIC5 (14% identical), and 2 more.
Diseases named in the same sentence as AEBP2 in open-access papers:
AEBP2 is named in the same sentence as 15 diseases in open-access papers, as found by Europe PMC text mining. Sharing a sentence is not in itself a finding about the gene and the disease. The quoted sentences say what the papers report.
Waardenburg syndrome (3 papers, 2013 to 2019). A disorder characterized by varying degrees of deafness and minor defects in structures arising from neural crest, including pigmentation anomalies of eyes, hair, and skin. "Mutations in Aebp2 in mice result in an enlarged colon, hypopigmentation and auditory defects similar to human Hirschsprung's disease and Waardenburg syndrome." (PMID 24324618, 2013). "Heterozygous mutant mice, with respect to the Aebp2 gene, which encodes for a component of PRC2 expressed in NCCs, show similar phenotypes to HSCR and Waardenburg syndrome patients." (PMID 31247956, 2019). "For example, Aebp2, an epigenetic DNA-binding protein involved in Hirschsprung's disease and Waardenburg syndrome, and Kcnj16, a potassium channel involved in respiratory response to hypoxia during breathing, showed VPA-restored expression changes, but the p value was greater than 0.05." (PMID 24968028, 2014). "Therefore, Aebp2 misregulation might be responsible for HSCR and the Waardenburg syndrome due to an aberrant epigenetic regulation of neural crest genes." (PMID 31247956, 2019).
breast cancer (2 papers, 2025). A primary or metastatic malignant neoplasm involving the breast. "To exclude the system interference in HP5008 cells, we conducted CRISPR-Cas9 knockouts of Rad51b, Ezh2, Suz12 and Aebp2 in Brca1-mutant 545 cells, which were isolated from a primary mammary tumor of a Brca1-MSK mouse." (PMID 41318657, 2025). "Although evidence of miRNA-mediated regulation of AEBP2 is limited, recent studies have identified AEBP2 as a functional target of miR-451a in breast cancer, forming part of a miRNA network that influences proliferation, apoptosis, migration, and invasion." (PMID 41009685, 2025).
Obesity (2 papers, 2018 to 2025). Accumulation of substantial excess body fat. "Methylation loci associated with obesity (AEBP2), calcium signaling (CAPNS1), insulin signaling (INSR, PTPRN2, RPTOR) and vasodilation (VASP) also appeared to be epigenome-wide significant." (PMID 29692868, 2018). "In addition to the findings of these immune-regulatory genes, many other top associations have been implicated in obesity (AEBP2) (FDR < 0.10), calcium signaling (CAPNS1), insulin signaling (INSR, PTPRN2, RPTOR), and vasodilation (VASP)." (PMID 29692868, 2018). "In TNBC tumors of AA patients with obesity, seventeen miRNAs, seven of which (miR-195-5p, miR-130a-3p, miR-130a-5p, miR-424-5p, miR-148a-3p, miR-374-5p, and miR-30a-5p) potentially downregulated two or more genes (e.g., CLCN4, PLCB1, CDC25B, AEBP2, ERBB4)." (PMID 41009685, 2025).
megacolon (1 paper, 2011). "Overall, the three phenotypes observed from the Aebp2+/β-Geo mice are similar to those observed from Waardenburg syndrome Type 4 (WS4): megacolon, hypopigmentation, and auditory defect." (PMID 21949878, 2011).
melanoma (1 paper, 2019). A malignant, usually aggressive tumor composed of atypical, neoplastic melanocytes. "Silencing of AEBP2 with long non coding RNA is associated to melanoma, while its deletion is observed in myeloid leukemia." (PMID 31568528, 2019).
myelodysplastic syndrome (1 paper, 2019). A clonal hematopoietic disorder characterized by dysplasia and ineffective hematopoiesis in one or more of the hematopoietic cell lines. "Deletion of other members of AEBP2 and polycomb suppression complex 2 is associated with secondary AML following chronic myeloproliferative neoplasms and myelodysplastic syndromes." (PMID 31417866, 2019).
ovarian carcinoma (1 paper, 2020). A malignant neoplasm originating from the surface ovarian epithelium. "β-Trcp regulates the Discs large homolog 5 (Dlg5) that inhibit HCC cell proliferation, and AE Binding Protein 2 (AEBP2) that induces ovarian cancer cells proliferation and cisplatin resistance." (PMID 32486158, 2020).
tumor (3 papers, 2019 to 2020). "Furthermore, expression of four proteins is associated with tumor progression/high risk AML: DOT1L, mTOR, VIM and ZNF521, whereas the expression of six proteins is associated with tumor suppression/low risk AML: AEBP2, CAST, CBFB, LSP1, MAP1S and probably PCBP1." (PMID 30634713, 2019). "To validate the results of bioinformatic analysis, we conducted a qRT-PCR for evaluation of hsa-miR-499a-5p, hsa-miR-499a-3p, AEBP2, and ZNEF1 expression levels of tumor samples in low-tobacco, medium-tobacco, and high-tobacco exposed HNSCC patients in our hospital." (PMID 31417866, 2019). "Furthermore, we validated the differential expression of hsa-miR-499a, AEBP2, and ZNRF1 in HNSCC patients with low, medium, and high tobacco exposure using tumor tissues of HNSCC patients from our research center by qRT-PCR." (PMID 31417866, 2019).
AEBP2 also shares sentences with these, for which no sentence is quoted: Hirschsprung disease (2 papers); leukemia (2); cancer (1); epilepsy (1); Macrocephaly (1); myeloid leukemia (1); oesophagus (1).